CCL5 (C-C motif chemokine ligand 5)
Diseases named in the same sentence as CCL5 in open-access papers (continued):
Sharing a sentence is not in itself a finding about the gene and the disease.
tumor (continued). "Nuclear focal adhesion kinase (FAK) was reported to induce Treg cell accumulation in the tumor milieu predominantly by modifying chemokine/cytokine and ligand-receptor crosstalk, including initiation of CCL5 transcription." (PMID 32425930, 2020). "For this reason, some postulate that cancer therapies should combine immunotherapy with increasing the expression of CCL5 in the tumor to enhance the infiltration of the tumor by various immune cells." (PMID 33076281, 2020). "In Nf1 murine optic gliomas, microglial production of a key growth factor (Ccl5) is both necessary and sufficient for tumor formation and growth." (PMID 32358581, 2020). "In Ret transgenic mouse models (melanoma model), tumor M-MDSCs also drove the recruitment of CCR5+ Treg cells through producing chemokines such as CCL3, CCL4 and CCL5, further accelerating tumor metastasis." (PMID 33613512, 2020). "Tumor tissues were collected after 24 days of treatment with anti-CCL5, anti-PD-L1, or anti-CCL-5 plus anti-PD-L1." (PMID 32300119, 2020). "An anti-CCL5 neutralizing antibody reduced tumor xenograft growth of GC cells coinjected with PBMCs." (PMID 32630699, 2020). "CCL5, a specific chemokine released by macrophages, regulates inflammation, of which its role in tumor progression is controversial." (PMID 33312950, 2020). "In this context, numerous studies in different tumor types have demonstrated the CCL5/CCR5 axis to be involved in tumor growth, metastasis, and the building of an immunosuppressive tumor-promoting TME." (PMID 32630699, 2020). "In this model, the combined blockade of CCL-5 and PD-L1 synergistically suppressed tumor growth by stimulating the activity of CD8+ cytotoxic T cells." (PMID 32300119, 2020). "CCL5, expressed by macrophages, DC and T-cells, promotes tumor proliferation, metastasis and invasion." (PMID 33138184, 2020). "C-C chemokine ligand 5 (CCL5) can promote the malignant process of tumor and be related to infiltration immune cells in some cancers, but not reported in KIRC." (PMID 33173412, 2020). "The combination of anti-CCL5 and anti-PD-L1 antibodies significantly upregulated the ratio of tumor-infiltrating CD8+ T cells." (PMID 32300119, 2020). "Accordingly, the overexpression of CCL5 or CCR5 by cancer cells or tumor tissues has been found to correlate with poor prognosis and CCR5 expression by cancer cells to associate with a decreased activity of DNA damaging agents." (PMID 32630699, 2020). "For various cancers, including LCa, the chemokine CCL5 (RANTES) facilitates tumor progression and metastasis." (PMID 32260550, 2020). "Increased CCL5 levels activate hypoxia inducible factor 2α and down-regulate tumor cell androgen receptor signals." (PMID 32630699, 2020). "We found that overexpression of CCL5 as well as LCMV treatment alone resulted in slightly decreased tumor growth and extended survival as in LCMV only treated mice." (PMID 32973762, 2020). "Both fibroblasts and MSCs are recruited by CCR5 ligands secreted by cancer cells, and are induced to secrete CCL5 and to become tumor-promoting CAFs." (PMID 32630699, 2020). "In tumor xenografts, inhibition of CCL5 with neutralizing anti-CCL5 antibodies decreased growth, liver metastasis and peritoneal carcinosis." (PMID 32630699, 2020). "Among the chemokine ligands tested, the CCR5 ligands CCL3 and CCL5 were remarkably upregulated in the tumour tissue compared to PTY cells or control skin." (PMID 32439888, 2020). "Concentrations of IL-2, IL-13 and CCL5 in the irradiated tumor were similarly decreased by DEX treatment." (PMID 32325715, 2020). "Recently, the immunofluorescence analysis of primary tumor and metastatic lymph node tissues showed a high colocalization of CCL5 with TAMs." (PMID 32630699, 2020). "The loss of Flt3L, CCL5, and XCL1 secretion by tumor-infiltrating NK cells impacts recruitment and survival of cross-presenting DCs, and correlates with increased tumor growth and responsiveness to anti-PD1 therapy." (PMID 32121071, 2020).
tumor (continued). "Here we observed that LCMV replication in tumor cells induces CCL5 production, which in turn leads to a strong and robust anti-tumoral NK cell cytotoxicity." (PMID 32973762, 2020). "Elevated CCL5 concentrations correlated with poorer histological differentiation, greater depth of tumor invasion, more frequent lymph node involvement, and advanced tumor stage." (PMID 33182840, 2020). "Despite the importance of CCL5 in inflammation, Trm T-cell homeostasis and tumor immunity, little is known about how the expression of the Ccl5 gene is regulated." (PMID 32218434, 2020). "In solid cancers, inflammatory chemokines such as CCL5 together with their receptors have been shown to attract neutrophils and monocytes at the tumor site and reprogram them, leading to altered immune response." (PMID 32399572, 2020). "In an EOC preclinical model, TH1 cells produced high levels of CCL5, enabling the recruitment and activation of DC in the tumor microenvironment, which eventually induces tumor-specific CD8+ T-cell activation." (PMID 32630708, 2020). "CCL5 expression has been detected in several tumor types including ovarian, prostate, pancreatic, and melanoma cancer." (PMID 32973762, 2020). "In a tumor, CCL5 expression is found in cancer cells, cancer-associated fibroblasts (CAF), mesenchymal stem cells (MSC), MDSC, TAM, and TIL." (PMID 33076281, 2020). "In another study, co-culture of tumor cells and MSCs elevated CCL5 expression in MSCs which increased invasive and migratory properties of tumor cells that express its receptor, CCR5, leading to increased metastases." (PMID 33414786, 2020). "This also shows that targeted recovery of RKIP expression in TNBC to reduce the secretion of CCL5 in tumor cells is an important strategy to reduce macrophage infiltration." (PMID 33224886, 2020). "CCL5 has a tumor-promoting role by inducing tumor cell proliferation, angiogenesis, and matrix metalloproteinases." (PMID 33381115, 2020). "Tumor-educated MSCs are immunosuppressive and tumor protective and, by secreting CCL5, they recruit CCR5+ monocytes." (PMID 32630699, 2020). "Among the top genes differentially expressed between sensitive and resistant cells, we identified a group of candidates related to tumor-microenvironment response (CCL5, CXCL10, IFIT3, IFI44, IFNL2)." (PMID 32365528, 2020). "A research had demonstrated that tumor-infiltrating Tregs were increased by doing intratumoral injection of CCL4 or CCL5 in mice models." (PMID 33173412, 2020). "In this study, the correlation between the expression levels of CCL5 in KIRC and some clinical features including the survival time, pathological stage, and so on, was analyzed to explore the value of CCL5 as a tumor biomarker in KIRC." (PMID 33173412, 2020). "Others used blocking mAbs to CCR5 or even one of its three ligands, CCL5, to inhibit metastasis and improve the survival of tumor-bearing mice and also enhance anti-PD1 efficacy in gastric cancer." (PMID 33193327, 2020). "Oestrogen has been reported to have an immunosuppressive effect in BC through the stimulation of CCL5 release in the tumour microenvironment." (PMID 33153211, 2020). "Several different regulatory factors, including Notch-1 and CCL5, are reportedly involved in the molecular mechanism of tumor-endothelial trans-differentiation." (PMID 33102474, 2020). "Among the various proteins secreted by TILs, host CCL5 is receiving much attention as a key anticancer molecule in mediating proper tumor immunity." (PMID 32218434, 2020). "Maraviroc decreases both MSC and monocyte recruitment by cHL cells and monocyte recruitment by CCL5-secreting tumor-educated bone marrow MSCs." (PMID 32630699, 2020). "The expression of chemokines for CCR2 (Ccl2 and Ccl7) or CCR5 (Ccl3, Ccl4, and Ccl5) in tumor-bearing lungs, chemoattractants for monocytes/macrophages, was unchanged in FROUNT-cKO mice." (PMID 32001710, 2020).
tumor (continued). "The combination epigenetic therapy (Aza + ITF-2357) induced the increased levels of CCL5, a secreted chemokine attracting functional lymphocytes, restraining tumor growth with increased number of CD8+ T cells in mice model of NSCLC." (PMID 32723974, 2020). "The accumulation of cDC1s in the tumor tissue has been attributed to several NK cell-derived cytokines such as CCL5, FLT3L, and XCL116,17." (PMID 33268774, 2020). "In a mouse BRAFV600E-mutant melanoma model, intratumoral NK cells upregulate Xcl1 and Ccl5 whereas NK cell depletion lowered the numbers of tumor-infiltrating cDC1." (PMID 33424862, 2020). "This tumor is characterized by an intratumoral accumulation of macrophages and high levels of CCL5 expression compared to sporadic adenomas or normal pituitary." (PMID 32630699, 2020). "We observed a decreased tumor burden in mice with combined treatment compared to the isotype control, anti-CCL5, or anti-PD-L1 alone." (PMID 32300119, 2020). "Accordingly, down-regulation of KLF5 inhibits the tumor-promoting effects of CAFs, which are restored by exogenous addition of CCL5." (PMID 32630699, 2020). "Although CCL5 and PD-L1 antibodies alone reduced the tumor burden, the antitumor effect was more dramatic in the mice treated with both antibodies." (PMID 32300119, 2020). "Collectively, our results suggest that RUNX3-mediated CCL5 repression is critical for modulating anti-tumor immunity." (PMID 32218434, 2020). "CCL5 was found to promote tumor recurrence by recruiting CCR5-expressing macrophages, which contribute to collagen deposition in residual tumors." (PMID 32630699, 2020). "Accordingly, miR-147-overexpressing cancer cells injected subcutaneously into mice inhibited tumor xenograft growth, showing reduced CCL5 expression, invasion, and decreased metastasis formation." (PMID 32630699, 2020). "When CCR5/CCL5 interaction is diminished or blocked, migration of Tregs to tumor is reduced, and even the size of tumor became smaller." (PMID 30987642, 2019). "CCL5 is an inflammatory chemokine known to mediate cross-talk between tumor cells and the tumor environment resulting in increasing amounts of tumor cell migration and invasion." (PMID 31341222, 2019). "We showed that, in tumor lesions, the local expression of PD-L1 positively associates with the expression of CD8, CCL5, CXCL10, and also IFN response signature from the TCGA datasets." (PMID 31221150, 2019). "Tumors expressing CCL5 recurred significantly earlier than control tumors, indicating that CCL5 expression is sufficient to accelerate tumor recurrence (p = 0.023; HR = 2.14)." (PMID 30990165, 2019). "Chemokine (C–C motif) ligand 5 (CCL5), which is associated with TLR signaling, was also upregulated in serum from tumor-bearing Rnf5−/− compared with WT mice." (PMID 30940817, 2019). "Tumor-derived CCL5 was detected in many clinical specimens and BC-derived cell lines, and were considered to promote BC aggressiveness." (PMID 31921621, 2019). "Through the targeting of Beclin1, it was discovered that high levels of CCL5 also increased infiltration of NK cells into the tumor." (PMID 31396523, 2019). "This shows that high levels of CCL5 appear to shorten the amount of time between tumor treatment and recurrence because CCL5 attracts macrophages that deposit collagen in the residual tumors." (PMID 30990165, 2019). "Tumor production of PGE2 impairs recruitment of NK cells responsible for CCL5 and XCL1 production, ultimately reducing intra-tumoral cDC1 migration leading to immune evasion and metastatic progression." (PMID 31921140, 2019). "CCL5 has been shown to play an important role in many facets of tumor progression, such as invasion, metastasis, neoangiogenesis, and immune cell infiltration." (PMID 30990165, 2019). "NK cells also promote recruitment of conventional DC-type 1 (cDCs) in the tumor microenvironment via secreted CCL5 and XCL1 cytokines." (PMID 30974896, 2019).
tumor (continued). "Functionally, CCL5 overexpression promotes macrophage recruitment, collagen deposition, and promotes tumor recurrence." (PMID 30990165, 2019). "Accordingly, we propose that GBE1 reduces the recruitment of CD8+ T cells into the tumor microenvironment by inactivating CCL5 and CXCL10, thus contributing to the immune escape in LUAD." (PMID 31221150, 2019). "VS-4718 can inhibit the expression of immunosuppressive molecules such as IL-33 and CCL5, and reduce Tregs in the tumor environment." (PMID 31186061, 2019). "Recent studies indicate the critical role of CCL4 and CCL5 within the tumor microenvironment is the recruitment of cells of myeloid lineage that support adaptive anti-tumor T cell responses, such as dendritic cells." (PMID 30873179, 2019). "Along the same lines, CCL5 was shown to recruit and skew macrophages towards a pro-tumor phenotype; blocking the corresponding receptor CCR5 induced tumor responses in a phase I clinical trial in advanced colorectal patients." (PMID 31067629, 2019). "Further, MDSCs have been reported to produce CCL3, CCL4, and CCL5 chemokines favoring tumor recruitment of Treg cells." (PMID 31484464, 2019). "The elevations in CXCL8 and CCL2 expression partly depended on direct physical contacts between the tumor cells and the MSCs/CAFs, whereas CCL5 up-regulation was entirely dependent on cell-to-cell contacts." (PMID 31031757, 2019). "In fact, IL-33 promoted eosinophil migration to the tumor indirectly, via induction of the chemokines CCL5 and CCL24/eotaxin-2 by tumor cells themselves." (PMID 31717819, 2019). "Elevated COX activity in tumor cells results in production of prostaglandin E2, which reduces NK cell infiltration and thus reduced the cDC1 recruitment factors XCL1 and CCL5 in the tumor microenvironment." (PMID 31849950, 2019). "MDSCs are recruited into the tumor site by the malignant cells by increasing the level of various soluble factors including IL-6, GM-CSF, TGFβ, VEGF and chemokines such as CCL2 and CCL5, in the tumor microenvironment." (PMID 31231358, 2019). "CCL5 is produced by PDA which encourages migration of Tregs into the tumor microenvironment due to their CCR5 expression." (PMID 30931508, 2019). "Our results suggest that a crosstalk between the tumor and its microenvironment plays a key role in the invasive nature of AIP-mutation-positive tumors and the CCL5/CCR5 pathway is a novel potential therapeutic target." (PMID 30867568, 2019). "We further demonstrate that depletion of GBE1 can upregulate CCL5 and CXCL10 expression through STING signaling to activate IFN-I pathway, potentiate T cell infiltration, and cause induced expression of PD-L1 on tumor cells simultaneously." (PMID 31221150, 2019). "For instance, NK cell-derived CCL5 in cooperation with XCL1 has been shown to drive DC1 recruitment into the tumor." (PMID 30873179, 2019). "Previous publications have indicated that CCL5 supported the tumor growth, invasion, and angiogenesis, as well as immune cell recruitment to the tumor microenvironment via the interaction with CCR5." (PMID 30813533, 2019). "We observe an increase in CCL5 levels during tumor regression and in residual tumors that is concomitant with immune cell infiltration." (PMID 30990165, 2019). "Both CCR5 and its ligand CCL5 are constitutively expressed by cHL-derived cell lines, by tumor cells from cHL lymph nodes, and by bystander cells including stromal cells and lymphocytes." (PMID 31096713, 2019). "We next engineered primary tumor cells to overexpress CCL5 or GFP as a control and used these cells in an orthotopic recurrence assay to test the effect of CCL5 expression on tumor recurrence." (PMID 30990165, 2019). "Mechanistically, we showed that the infiltration of NK cells is related to the ability of Beclin1-defective tumor cells to overexpress CCL5 cytokine responsible for the trafficking of NK cells to the tumor." (PMID 29922284, 2018).
tumor (continued). "With tumor-suppressor proteins present, CCL5 chemokine expression by tumor cells increased driving infiltration by inflammatory macrophages and CD8+ cytotoxic T cells and subsequently reduced tumor growth." (PMID 29755457, 2018). "Intracellular FACS analysis revealed that Ccl5 was produced nearly exclusively by memory CD8+ T cells in the tumor tissue of Sipa1−/− mice." (PMID 29500416, 2018). "The tight connection between the microbiota, the immune system, and intestinal tumorigenesis impacts tumor growth in two ways in vertebrates: Indirect tumor progression is mediated by factors such as CCL5 and cytokines like IL-17 and IL-23." (PMID 30294304, 2018). "The results of immunofluorescence staining showed that the number of CD8+ T cells infiltrated in the tumor of CCL5−/− mice was significantly higher than that in the control group, which was confirmed by the data of flow cytometry (FC) in CT26 mouse model." (PMID 29991744, 2018). "The results showed that there was no significant differential expression of LAG-3, TIM-3, and ICOS on CD8+ T cells between CCL5+/+ and CCL5−/− mice either from tumor or spleen." (PMID 29991744, 2018). "In this study, we demonstrated that CCL5-deficiency inhibited tumor growth and metastasis of CRC by increasing the infiltration of CD8+ T cells into central tumor area." (PMID 29991744, 2018). "This suggests that the expression of CCL5 is elevated in the drinking patients’ tumor microenvironment." (PMID 29872080, 2018). "To evaluate the potential biological relevance of the regulatory effect of cordycepin, we assessed the effect of CCL5 on the migration of tumor cells." (PMID 29844932, 2018). "There were not statistical differences in the clinopathological features, except in the residual tumor size with larger tumors in low TILs group (P = 0.017) and CCL5 (P = 0.053)." (PMID 29559701, 2018). "Taken the transcription of the chemokines in vivo and vitro together, CCL5 had greater difference between the parental and resistant cell, we further checked its expression in the tumor tissues by IHC." (PMID 30093664, 2018). "Wide range of studies have implied the involvement of CCL5/CCR5 signaling axis in anti-tumor immunity, invasion and metastasis." (PMID 29475434, 2018). "To demonstrate the important role of CD8+ T cells in CCL5-deficiency-mediated tumor regression of CRC, we performed antibody-mediated CD8+ T-cell depletion in CCL5+/+ and CCL5−/− mice to examine the tumor growth and metastasis." (PMID 29991744, 2018). "This suggests that CCL5 induced by a specific tumor microenvironment prevents the MAMs to become tumoricidal cells." (PMID 30483271, 2018). "In vitro analysis showed that tumor-derived PGE2 resulted in diminished secretion of CCL5 and XCL1 by NK cells and increased NK cell death." (PMID 29986768, 2018). "Tumor-associated macrophages (TAMs) are macrophages that are recruited to the TME by chemokines such as CCL2 (MCP-1) and CCL5 (RANTES)." (PMID 29652813, 2018). "CC chemokines, especially MCP1 (CCL2) and CCL5, are major attractants of monocyte and macrophage precursors to the tumor microenvironment." (PMID 29573228, 2018). "show that tumor regression occurs in sequential steps involving the activation of the innate immune system and immune infiltration of the tumor, and they identify CCL5 as a possible driver of regression." (PMID 29634949, 2018). "Tumor‐derived chemotactic factors such as Ccl2, Ccl3, Ccl5, and Ccl7 are known to recruit macrophages to the growing tumor." (PMID 29047229, 2018). "The expression of CCL5 was much higher in the parental tumor cells after RT than that in the resistant tumor." (PMID 30093664, 2018). "Patients in the high CCL5 group also had stronger CCL5 immunohistochemistry (IHC) staining in tumor tissues and in metastatic lymph nodes." (PMID 29772686, 2018). "Mesenchymal stem cells are induced by tumor cells to secret CCL5 to enhance motility and metastasis." (PMID 29559701, 2018).